TYMP (thymidine phosphorylase)
Diseases named in the same sentence as TYMP in open-access papers (continued):
Sharing a sentence is not in itself a finding about the gene and the disease.
breast carcinoma (17 papers, 2004 to 2025). "Breast cancer cells are characterized by the overexpression of thymidine phosphorylase, which catalyzes the breakdown of thymidine to thymine and 2-deoxyribose-1-phosphate." (PMID 38785550, 2024). "Our study has outlined that Thymidine Phosphorylase is over-expressed immunohistochemically in canine malignant mammary tumors." (PMID 31709268, 2019). "The enzyme responsible for the final step is thymidine phosphorylase (TP), which is overexpressed in breast cancer." (PMID 22396769, 2012). "Thymidine phosphorylase is indeed upregulated by several anticancer drugs in human breast cancer cells, including both tumour and stromal cells; however, there are variations in the level." (PMID 15150550, 2004). "STAT1 plays a key role in regulating the effect of chemotherapy; TYMP is considered to be a potential prognostic marker for ovarian cancer and breast cancer; GBP5, as an immune response regulator, can affect tumor progression; and PSME2 is closely related to the progression of various tumors." (PMID 40259929, 2025). "Furthermore, VPA has been shown to demonstrate anti-cancer activity in breast cancer via induction of TP or thymidine phosphorylase expression." (PMID 30050438, 2018). "Capecitabine, which is commonly used for metastatic breast cancer in different settings, is an inactive prodrug that takes advantage of elevated levels of thymidine phosphorylase (TP), a key enzyme that is required for its conversion to 5-fluororacil, in tumors." (PMID 26735339, 2016). "TYMP has been shown to increase in tumor samples of patients receiving anthracycline-and taxane-based preoperative chemotherapy for breast cancer and this observation provided the rationale for several studies which evaluated the addition of capecitabine to taxane-based therapy 22–24." (PMID 24464780, 2014). "Researchers found derivatives and with the highest potency against breast cancer cell line (MCF-7), as well as thymidine phosphorylase enzyme inhibitory activity, as compared to the reference drugs adriamycin and 7-deazaxanthin, respectively." (PMID 37259401, 2023). "Based on this background, we evaluated whether the mRNA expression of thymidylate synthase, thymidine phosphorylase, and DPYD was altered in the TAM-resistant breast cancer sublines." (PMID 34101751, 2021). "Breast cancer is the most common cancer among women and is studied as an angiogenic carcinoma due to the high expression levels of proangiogenic factors, such as VEGFs, HIF-1α, TGF-β, or thymidine phosphorylase (TP), in carcinoma cells." (PMID 22007214, 2012). "Thus, discovered that valproic acid increased the activity of capecitabine in breast cancer cells after suppressing histone deacetylase 3; although, this impact was eliminated in cells lacking thymidine phosphorylase." (PMID 36942277, 2023).
colorectal cancer (17 papers, 1999 to 2025). A primary or metastatic malignant neoplasm that affects the colon or rectum. "Another study found that TYMP-induced T cell exhaustion plays a critical role in immunotherapy resistance in colorectal cancer (CRC)." (PMID 40303404, 2025). "The only approved drug targeting TYMP found in our study is tipiracil, a potent inhibitor of TYMP that is used in the treatment of colorectal carcinoma." (PMID 35573665, 2022). "In term of molecular mechanism, VPA was showed to synergize with fluoropyrimidines in against breast and colorectal cancer via downregulating thymidylate synthase and upregulating thymidine phosphorylase." (PMID 30961642, 2019). "Previously identified predictive chemosensitivity markers for UFT/LV chemotherapy in colorectal cancer include high mRNA expression levels of 5-FU metabolism-related enzymes, orotate phosphoribosyltransferase and thymidine phosphorylase." (PMID 24649225, 2013). "TYMP is overexpressed in various cancers, including breast cancer, gastric cancer, esophageal cancer, oral squamous cell carcinoma, lung cancer, colorectal cancer, cervical cancer, and bladder cancer." (PMID 40303404, 2025). "However, the TPI, a TYMP inhibitor approved by the US FDA, was associated with a better overall survival of refractory colorectal cancer patients." (PMID 35734412, 2022). "Interestingly, Ishitsuka and colleagues previously showed that various cytostatic drugs had increased the level of TYMP expression in WiDr human colorectal cancer xenografts, which was most pronounced by Taxol, Taxotere and Mitomycin C." (PMID 33874986, 2021). "High thymidine phosphorylase (TYMP, OMIM: 131222, 5-FU activating enzyme) transcript level was associated with significantly better disease-free survival (DFS) following oral administration of 5-FU in stage III colorectal cancer patients." (PMID 27733154, 2016). "The TYMP-targeting drug TAS-102, a trifluridine-tipiracil hydrochloride mixture, is currently approved for treating advanced colorectal cancer and gastric cancer after at least two lines of chemotherapy." (PMID 39548315, 2025). "Thymidine-phosphorylase (TP) expression was increased in the cytoplasm in patients with laryngeal cancer without confirming the results obtained in colorectal cancer studies (TP values correlated with the favorable response in patients treated with capecitabine and irinotecan)." (PMID 36233450, 2022). "TYMP expression in various solid tumors, such as head–neck, breast, lung, oral squamous carcinoma, esophageal, gastric, bladder, prostate, ovarian, and cervical cancers, is higher than that in adjacent noncancerous tissues, including colorectal carcinomas." (PMID 36090972, 2022). "Similarly, the results of studies indicating potential prognostic role of DPYD or TYMP expression for survival of colorectal cancer patients after 5-FU-treatment were not replicated." (PMID 27733154, 2016).
COVID-19 (13 papers, 2020 to 2026). A disease caused by infection with severe acute respiratory syndrome coronavirus 2. "The plasma concentration of TYMP has been proposed to be an acuity marker for COVID-19 diagnosis and has been associated with inflammation and organ damage, hallmarks of the disease." (PMID 35967328, 2022). "TYMP expression was increased in diabetic patients, which are a high-risk cohort to develop severe COVID-19." (PMID 33829029, 2021). "TYMP represents a potential therapeutic target to mitigate long-term pulmonary consequences of COVID-19." (PMID 41988188, 2026). "We recently demonstrated that TYMP expression is increased in COVID-19 patients and its expression is significantly correlated with COVID-19-associated inflammation and thrombosis." (PMID 39742002, 2024). "TYMP and RIG-I were recently identified as part of a 22-protein signature associated with fatal COVID-19 in a proteomics study." (PMID 37100811, 2023). "Genes impacting mitochondrial function include 31 of 37 in mitochondrial DNA and nuclear genes encoding mitochondrial proteins, including ten EDS-related (NDUFA-11/S3, OPA1, TYMP, etc.)and three COVID-19-related (STAT2, TLR3, NDUFAF7) genes." (PMID 37504295, 2023). "In comparing with non-COVID-19 patients, COVID-19 patients, even those who were discharged from the emergency department (A6) had a significantly high level of plasma TYMP (p = 0.0003)." (PMID 33829029, 2021). "Taken together, our study, for the first time, indicates that plasma TYMP is correlated with thrombotic events, inflammation, and tissue damages in COVID-19 patients." (PMID 33829029, 2021). "However, TYMP expression was significantly increased in COVID-19 patients with respiratory symptoms when compared with COVID-19 patients without respiratory symptoms." (PMID 33829029, 2021). "Samples collected from 358 patients (284 are COVID-19) on day 0, 202 patients (197 are COVID-19) on day 3, and 131 patients (all are COVID-19) on day 7, as well as 42 patients who died from COVID-19 within 28 days, were extracted for analyzing TYMP expression." (PMID 33829029, 2021). "However, TYMP expression at day 0 was lower in the COVID-19 patients who had primary heart or lung diseases." (PMID 33829029, 2021). "Based on these pre-clinical and clinical studies, we tested the hypothesis that TYMP plays an important role in the SARS-CoV-2-induced inflammation and the COVID-19 associated thrombosis." (PMID 33829029, 2021). "However, in a dual-center, two-cohort study, TYMP levels in monocytes of COVID-19 patients were increased in a range of 2.0- to 35-fold, in a monocyte-type dependent manner." (PMID 33829029, 2021). "Plasma TYMP is also positively correlated with COVID-19 patients who had respiratory symptoms." (PMID 33829029, 2021). "Targeting TYMP with tipiracil, a selective TYMP inhibitor, which has been approved by the Food and Drug Administration for clinical use, could be a novel effective medicine for COVID-19." (PMID 33829029, 2021). "TYMP may be a novel and sensitive acuity marker for patients with COVID-19." (PMID 33829029, 2021). "Targeting TYMP with TPI could be a potentially effective therapy for COVID-19." (PMID 33829029, 2021). "The acuity assessed using the WHO Ordinal Outcomes Score for day 0 was not different between patients with and without heart or lung disease, suggesting that the primary lung or heart disease associated low-TYMP expression in the patients with COVID-19 does not reflect the acuity." (PMID 33829029, 2021). "The ODF3B (ciliary microtubule associated protein 1B)–SCO2 (synthesis of cytochrome c oxidase 2) (OS) and TYMP (thymidine phosphorylase)-SCO2 (TS) chimeric isoforms made up the majority of the 14 chimeras found only in the PTBP1 knockdown and COVID-19 samples." (PMID 40110491, 2025). "In random forest models for COVID-19, CST5, DPP7, NADK, KYAT1 and TYMP showed the highest variable importance." (PMID 35967328, 2022).
COVID-19 (continued). "In the non-COVID-19 patients, even their plasma level of CRP was above 60–180 mg/L, their TYMP expression was still significantly lower than in the COVID-19 patients with CRP < 20 mg/L (p = 0.025)." (PMID 33829029, 2021). "Since red blood cells do not express TYMP and TYMP is not a secreted protein, we consider that the increased plasma TYMP in COVID-19 patients was from either thrombolysis of the platelet-rich thrombi or organ damage." (PMID 33829029, 2021). "We found plasma TYMP were significantly increased in COVID-19 patients on day 0, 3, and 7 when compared with non-COVID-19 patients." (PMID 33829029, 2021). "In non-COVID-19 patients, TYMP expression was similar between patients with and without heart or lung disease." (PMID 33829029, 2021). "Primary kidney diseases, hypertension, and pre-existing immunocompromised conditions, as well as pre-existing gastrointestinal diseases and diabetes also did not affect TYMP expression in both COVID-19 positive and negative patients." (PMID 33829029, 2021). "Patients who died from COVID-19 also had a higher level of plasma TYMP compared with non-COVID-19 patients." (PMID 33829029, 2021). "However, since the numbers of classical, intermediate, and non-classical monocytes decreased in COVID-19 patients, the increase of TYMP in these particular monocyte populations may not account for the increased plasma TYMP." (PMID 33829029, 2021). "Our findings suggest that TYMP is a more sensitive and specific marker for COVID-19 because in the COVID-19 patients with the lowest CRP (<20 mg/L), their TYMP expression was significantly higher than the non-COVID-19 patients, even they have a very high level of plasma CRP (>60–180 mg/L)." (PMID 33829029, 2021).
gastric cancer (12 papers, 1996 to 2025). A primary or metastatic malignant neoplasm involving the stomach. "TYMP increases the migration and invasion of gastric cancer cells and is associated with poorer survival rate." (PMID 27283904, 2016). "We explored its prognostic value in localized gastric cancer (GC) after R0 resection and the potential associations with Thymidine phosphorylase (TYMP), which was reported to increase the migration and invasion of gastric cancer cells." (PMID 27283904, 2016). "Literature showed S-1 was better in patients with high dihydropyrimidine dehydrogenase, while capecitabine was reported to be more effective in high thymidine phosphorylase gastric cancer." (PMID 24349363, 2013). "In contrast, thymidine phosphorylase mRNA was higher in cancer cells than in cancerous stroma in gastric cancer (p < 0.0001) and lower in cancer cells than in cancerous stroma in colon cancer (P = 0.0055)." (PMID 18652704, 2008). "Suppression of thymidine phosphorylase could enhance the drug responsiveness of gastric cancer cell to 5-fluorouracil, and the results indicated that “nucleotide metabolism” was also closely associated with chemotherapy." (PMID 37252635, 2023). "In many cases, poor prognosis is associated with TYMP-positive versus TYMP-negative colons and differentiated gastric carcinomas." (PMID 36090972, 2022). "In Chinese advanced gastric cancer, Thymidine Phosphorylase positive & β-tubulin III negative might predict response and prognosis to capecitabine plus paclitaxel chemotherapy." (PMID 21586171, 2011).
ovarian carcinoma (11 papers, 2003 to 2026). A malignant neoplasm originating from the surface ovarian epithelium. "TYMP had the highest percentage of mutation, especially in ovarian epithelial cancer, while UCK1, which is frequently mutated in endometrial carcinoma, is the less present among the screened genes." (PMID 32887417, 2020). "Higher expression levels of thymidine phosphorylase are found in certain histologic types of ovarian cancer compared to healthy ovarian tissue." (PMID 18794792, 2008). "A similar observation has been reported in cell culture experiments combining paclitaxel and another prodrug of 5-fluorouracil, furtulon, in ovarian cancer in vitro, even after induction of thymidine phosphorylase." (PMID 17640356, 2007). "The potential for capecitabine to be used in combination with agents that upregulate thymidine phosphorylase in relapsed ovarian cancer is clear." (PMID 14612890, 2003). "Consequently, we generated TYMP-overexpressing ID8 (mouse) ovarian cancer cell lines and established an orthotopic syngeneic mouse model by inoculating ID8Luc+ cells into the ovarian bursal cavity of C57/BL6 mice." (PMID 39548315, 2025). "Capecitabine is absorbed through the intestinal mucosa as an intact molecule and is converted to 5-FU via a three-step enzymatic activation cascade, involving thymidine phosphorylase and cytidine deaminase, both of which are upregulated in ovarian cancer cells." (PMID 14612890, 2003). "Notably, eight proteins upregulated in the invasive stroma (NNMT, FCGR1A, FCER1G, TYMP, F13A1, DCK, CASP3, and SYK) represented FDA-approved drug targets outside of ovarian cancer, emphasizing their high relevance for future preclinical investigations." (PMID 41233595, 2026).
colon carcinoma (7 papers, 2003 to 2022). "This is supported by experimental studies in which enhanced 5-FU cytotoxicity is observed in conditions where TYMP is upregulated in colon cancer cells and xenograft mice." (PMID 34571731, 2021). "In a human colon cancer xenograft model, thymidine phosphorylase was upregulated, and synergy with PX was observed." (PMID 24959275, 2014). "In vitro, the expression of thymidine phosphorylase was subject to little variation after exposure of naive colon tumour cells to FU." (PMID 12618890, 2003). "The gene expression of TYMP was higher in colon tumors compared to rectal tumors, and both macTYMP and tecTYMP, but not stromaTYMP expression was significantly higher in right-sided compared to left-sided colon tumors." (PMID 35567733, 2022). "In colon cancer cells, 5-FU is predominantly converted to ribonucleotides via OPRT (encoded by UMPS), and in SCLC the downregulation of TYMP coupled with moderately upregulated UMPS (log2FC = 0.37) is consistent with 5-FU also being predominantly converted to ribonucleotides." (PMID 32224870, 2020). "To conclude, in this study, we have demonstrated for the first time that FOXM1 has a crucial role in 5-FU drug resistance in colon cancer cells, through regulating some of the main 5-FU targets, including TYMS, TK-1 and TYMP." (PMID 30728402, 2019). "Other small molecule inhibitors studied to be effective in reversing 5-FU in colon cancer cells may include phospholipase A2 inhibitor quinacrine that enhances c-Jun N-terminal kinase (JNK1)-dependent Nrf2 degradation, and DNA methyltransferase inhibitor decitabine that demethylates TYMP promoter." (PMID 34571731, 2021).
lung carcinoma (7 papers, 1993 to 2023). "Chemotherapy increases CDA and TYMP expression thereby rendering resistant lung cancer cells susceptible to subsequent 5′-DFCR treatment." (PMID 33874986, 2021). "In lung cancer treatment, when the PI3K-Akt pathway is inactivated, curcumin (DMC) enhanced the sensitivity of drug-resistant lung cancer cells to cisplatin by downregulating the expression of thymidine phosphorylase and RCC1." (PMID 35684449, 2022). "S100-A8, thymidine phosphorylase, annexin A2, transglutaminase 2, and annexin A1 were lung cancer individuals’ most renowned over-expressed proteins." (PMID 36552956, 2022). "In summary, treatment with chemotherapy results in increased CDA/TYMP expression during the recovery phase thereby sensitizing lung cancer cells to subsequent 5′-DFCR treatment." (PMID 33874986, 2021). "We found that treatment with chemotherapy results in increased CDA/TYMP expression during the recovery phase thereby sensitizing lung cancer cells to subsequent 5′-DFCR treatment." (PMID 33874986, 2021). "Further, the increase of CDA and TYMP expression after treatment with chemotherapy was more pronounced in KRAS mutant lung cancer cells." (PMID 33874986, 2021). "A recent report highlighted Pyr demonstrates promising anti-cancer and anti-metastatic activity in lung cancer through dual targeting of DHFR and thymidine phosphorylase (TP)." (PMID 36837770, 2023). "Thus, our study reveals that the chemotherapy-induced increase in pyrimidine salvage pathway expression, e.g., increased CDA and TYMP, might be exploited in the clinical setting to target therapy-resistant lung cancer by schedule-dependent treatment with Capecitabine." (PMID 33874986, 2021). "5′-DFCR was found to selectively inhibit the growth of chemotherapy-resistant lung cancer cells featuring increased CDA and TYMP expression." (PMID 33874986, 2021).
metastatic colorectal cancer (6 papers, 2014 to 2026). "Several clinical studies have indicated that TYMP expression is associated with time to progression in patients with metastatic colorectal cancer." (PMID 36090972, 2022). "For example, thymidine phosphorylase (TYMP), a therapeutic target in metastatic colorectal cancer, showed a strong and gradual increase in the invasive stroma." (PMID 41233595, 2026). "TAS-102 (Lonsurf) is an oral cytotoxic drug that has a nucleoside analog (trifluridine) and a thymidine phosphorylase inhibitor (tipiracil) approved for use in refractory metastatic colorectal cancer." (PMID 32154019, 2019).
bladder cancer (5 papers, 2005 to 2024). "TYMP was associated with the regulation of the digestive system process, pentosyltransferase activity, pyrimidine metabolism, nucleoside metabolic process, regulation of transmission of nerve impulses, drug metabolism, and bladder cancer." (PMID 39023413, 2024). "Some of the proteins such as SERPINA1, FGG, FGA, APOA1 and HP were also found with differential abundance in urine in proteomics studies of bladder cancer, and TYMP in tissue in renal cell carcinoma, but mostly with opposite abundance level compared to our study." (PMID 25653573, 2015).